METTL5 (methyltransferase 5, N6-adenosine)
Description:
Catalytic subunit of a heterodimer with TRMT112, which specifically methylates the 6th position of adenine in position 1832 of 18S rRNA. N6-methylation of adenine(1832) in 18S rRNA resides in the decoding center of 18S rRNA and is required for translation and embryonic stem cells (ESCs) pluripotency and differentiation.
Synonyms: HSPC133; MRT72
Tractability: PROTAC: ubiquitination databases record sites on it.
Gene: Protein-coding gene on chromosome 2 (169,810,081 to 169,824,931, reverse strand). Ensembl gene ENSG00000138382.
Subcellular location: Nucleus; Presynapse; Postsynapse
Subcellular location (Human Protein Atlas): Nucleoli; Nucleoli fibrillar center; Cytosol
Gene Ontology:
Molecular function: protein binding; rRNA (adenine-N6-)-methyltransferase activity; S-adenosyl-L-methionine binding; methyltransferase activity; N-methyltransferase activity; nucleic acid binding; S-adenosylmethionine-dependent methyltransferase activity
Biological process: positive regulation of translation; rRNA methylation; rRNA processing; stem cell differentiation
Cellular component: cytoplasm; fibrillar center; nucleolus; nucleus; postsynapse; presynapse; RNA N6-methyladenosine methyltransferase complex
Genetic constraint (gnomAD): Loss-of-function variants: 20 observed, 15.62 expected, observed/expected ratio (o/e) 1.28, 90% interval 0.9 to 1.8. The upper end of that interval is the gene's LOEUF score, 1.8, which puts it in group 6 of 6, group 1 being the genes least tolerant of losing a copy. Missense variants: 181 observed, 200.77 expected, observed/expected ratio (o/e) 0.9, 90% interval 0.8 to 1.02. Synonymous variants: 71 observed, 69.72 expected, observed/expected ratio (o/e) 1.02, 90% interval 0.84 to 1.24.
Homologues: Orthologues: macaque METTL5 (99% identical), chimpanzee METTL5 (96% identical), dog METTL5 (95% identical), guinea pig METTL5 (93% identical), rabbit METTL5 (93% identical), mouse Mettl5 (91% identical), pig METTL5 (91% identical), rat Mettl5 (81% identical), zebrafish mettl5 (75% identical), tropical clawed frog mettl5 (64% identical), Drosophila melanogaster Mettl5 (59% identical), Caenorhabditis elegans metl-5 (43% identical).
Diseases named in the same sentence as METTL5 in open-access papers:
METTL5 is named in the same sentence as 53 diseases in open-access papers, as found by Europe PMC text mining. Sharing a sentence is not in itself a finding about the gene and the disease. The quoted sentences say what the papers report.
hepatocellular carcinoma (10 papers, 2023 to 2025). A malignant tumor that arises from hepatocytes. "METTL5 has been confirmed to be overexpressed in a variety of tumors and affects patient prognosis, such as hepatocellular carcinoma, Intrahepatic cholangiocarcinoma (ICC), and breast cancer." (PMID 40018408, 2025). "The Myc pathway is inhibited to downregulate PD-L1 expression and immune escape of hepatocellular carcinoma cells when Mettl5 is knocked down, as found by Xu and colleagues." (PMID 40391221, 2025). "In hepatocellular carcinoma, METTL5 was shown to promote immune evasion through immune checkpoint regulation." (PMID 41487998, 2025). "Hepatocellular carcinoma (HCC) overexpresses the N6‐methyltransferase METTL5 which correlates with malignant cell behavior and poor prognosis." (PMID 38613157, 2024). "Hepatocellular carcinoma overexpresses the N6‐methyltransferase METTL5 which correlates with malignant cell behavior and poor prognosis." (PMID 38613157, 2024). "We constructed a METTL5 knockdown hepatocellular carcinoma cell line model and an animal model to determine the effect of METTL5 on hepatocellular carcinoma progression." (PMID 38613157, 2024). "The m6A methyltransferase METTL5 is overexpressed in hepatocellular carcinoma (HCC) and correlates with poor prognosis." (PMID 38613157, 2024). "We found that METTL5 expression was elevated in hepatocellular carcinoma tissues and correlated with poor patient prognosis, and in the analysis of clinicopathological features showed a correlation with TNM staging." (PMID 38613157, 2024). "In hepatocellular carcinoma cell lines with knockdown of METTL5, the malignant biological behavior was significantly reduced both in vitro and in vivo." (PMID 38613157, 2024). "METTL5 regulates hepatocellular carcinoma (HCC) proliferation through numerous pro-oncogenic USP5-c-Myc signaling cascades." (PMID 39289775, 2024). "Such as, METTL5 stabilizes c-Myc to reprogram glucose metabolism in hepatocellular carcinoma." (PMID 40018408, 2025). "METTL5 overexpression led to the progression of hepatocellular carcinoma (HCC) both in vitro and in mice." (PMID 37047306, 2023). "Despite the abnormal expression of 18S rRNA m6A methyltransferase METTL5 being reported in some types of human malignancies, but its effect on hepatocellular carcinoma (HCC) remains to be unclear." (PMID 37400463, 2023).
breast carcinoma (9 papers, 2021 to 2026). "METTL5, an 18S rRNA methyltransferase, was also found to be elevated in patients with breast cancer, and its expression correlated with poorer outcomes." (PMID 37047306, 2023). "METTL5 expression was upregulated in breast cancer tissues and was necessary for the growth of breast cancer cell lines." (PMID 36835633, 2023). "Among the four m6A regulators, METTL5 was confirmed to serve as the enzyme for the m6A modification of 18S rRNA, thereby promoting breast cancer cell growth." (PMID 34238292, 2021). "A previous study reported that METTL5 is crucial for breast cancer cell growth." (PMID 37400463, 2023). "Dysregulation of METTL5 has been revealed in breast cancer, pancreatic cancer and gastric cancer." (PMID 37033963, 2023). "Furthermore, the expression of METTL5, which has been reported to promote breast cancer growth, was lower in MCF7 and MDA-MB-231 compared to MCF10-A at the mRNA level, but higher at the protein level." (PMID 36725888, 2023). "Even though METTL5 is overexpressed in the breast cancer cell lines, it is known to deposit m6A in the 18S ribosomal RNA; and given that m6A levels in mRNA were also higher in MCF7 and MDA-MB-231 cells, we aimed to understand the contribution of m6A in mRNA during breast tumorigenesis." (PMID 36725888, 2023). "This suggested that post-transcriptional regulation of METTL5 may occur during the acquisition of the breast cancer phenotype." (PMID 36725888, 2023). "In addition, METTL5 has been reported to promote translation initiation and cell growth in breast cancer." (PMID 34702266, 2021). "It was reported that the expression METTL5 protein was increased in breast cancer specimens." (PMID 34702266, 2021). "Surprisingly, while METTL5 expression was required for the growth of some breast cancer cells lines, it did not affect the growth of the breast cancer cell line MCF7, nor of other cancer cell lines such as HeLa, HCT116, or HAP1." (PMID 37047306, 2023).
liver cancer (6 papers, 2023 to 2025). An epithelial or non-epithelial malignant neoplasm that arises from the liver. "As compared to human normal liver cells, liver cancer cell lines expressed significantly higher levels of METTL5." (PMID 38613157, 2024). "METTL5 protein expression was substantially elevated in liver cancer when compared with paired healthy tissues." (PMID 37400463, 2023). "METTL5 protein expression was substantially elevated in liver cancer when compared with paired normal tissues through the UALCAN database." (PMID 37400463, 2023). "Furthermore, proliferation, migration, and invasion of liver cancer cells were suppressed when METTL5 was inhibited, increased cell apoptosis, and consequently hindered liver cancer progression." (PMID 38613157, 2024). "Cell lines with liver cancer expressed less METTL5 protein after transfection." (PMID 38613157, 2024). "Furthermore, the METTL5 gene expression gradually increased with the development of the severity of liver cancer." (PMID 37400463, 2023). "Recent studies on METTL5 have focused on glucose and fat metabolism as well as immune-related regulation, where researchers recently found a positive correlation between METTL5 expression and the infiltration of B cells, CD8+ T cells, CD4+ T cells, macrophages, neutrophils, and DCs in liver cancer." (PMID 39199429, 2024). "In addition, an increasing number of studies indicated that this gene influences glycolysis in target cells via different pathways, such as the METTL5/cMyc/TPI1 pathway, thereby affecting the onset and prognosis of various diseases, including lung cancer, liver cancer, and myopia." (PMID 40746540, 2025).
Intellectual disability (5 papers, 2022 to 2025). "TRMT112 is indispensable for the stability of METTL5, and mutations in METTL5 associated with microcephaly and intellectual disability disrupt this protein–protein interaction, underscoring its pathological significance in neurodevelopment." (PMID 41487998, 2025). "Clinical studies have shown that METTL5 mutations, which impair 18S rRNA m6A modification, are associated with intellectual disability, microcephaly, and craniofacial abnormalities." (PMID 41487998, 2025). "In mouse embryonic stem cells (mESCs), Mettl5 knockout leads to abnormal craniofacial and neural development, and knockout mice display intellectual disability, recapitulating human pathogenic phenotypes." (PMID 41487998, 2025). "Clinical studies have revealed that mutations in METTL5, the methyltransferase responsible for 18S rRNA m6A modification, can result in intellectual disability, microcephaly, and craniofacial anomalies." (PMID 41487998, 2025). "Mutations in the METTL5 gene in humans cause intellectual disability and developmental abnormalities, and studies in model organisms further suggest a role in development." (PMID 36266443, 2022). "Our work supports findings that TRMT112 is required for METTL5 stability and reveals that human METTL5 mutations associated with microcephaly and intellectual disability disrupt this interaction." (PMID 35033535, 2022). "Future studies are needed to discern the functional impact of the METTL5G61D mutation as well as the mechanistic role that METTL5 plays in human brain development and intellectual disability." (PMID 36266443, 2022). "Furthermore, mutations in METTL5, linked to microcephaly and intellectual disability, disrupt its interaction with tRNA methyltransferase activator subunit 11−2 (TRMT112), affecting ribosomal function." (PMID 38797935, 2024). "Since METTL5 mutations are associated with intellectual disabilities in human patients, we wanted to determine whether cognitive or behavioral changes were evident in our mouse model." (PMID 35033535, 2022). "Since mutations in METTL5 have also been found in human patients with intellectual disability and microcephaly we introduced two of these human variants into our FLAG-METTL5 construct, G61D and K191Vfs∗10 (a 2 bp deletion that results in a K > V point mutation and premature stop)." (PMID 35033535, 2022). "METTL5 gene mutations are linked with intellectual disabilities." (PMID 36266443, 2022). "Biallelic variants in METTL5 have been linked to autosomal recessive intellectual developmental disorder-72 (MRT72), typically presenting with microcephaly, intellectual disability, and speech delay." (PMID 41465175, 2025). "Moreover, in METTL5 knockout mouse models, defects in craniofacial and nervous development are observed, along with intellectual disabilities and disrupted myelination processes." (PMID 38797935, 2024). "More specifically, mutations in METTL5 have been implicated in developmental abnormalities including microcephaly, intellectual disabilities, and attention deficit hyperactivity disorder (ADHD), but until recently very little was known about METTL5 function." (PMID 35033535, 2022).
microcephaly (5 papers, 2021 to 2025). A congenital or acquired developmental disorder in which the circumference of the head is smaller than normal for the person's age and sex. "Mutations in METTL5 were found to be associated with mild to severe forms of ID, with symptoms including muscular hypotonia, seizures, microcephaly, short stature, and malformations." (PMID 36266443, 2022). "At the same time, the bi-allelic variants in METTL5 resulting in truncated METTL5 with a missing C-terminus causes autosomal-recessive intellectual disability and microcephaly, highlighting its essential role in brain development and cognitive function." (PMID 34948388, 2021). "Biallelic METTL5 variants have previously been linked to autosomal recessive intellectual developmental disorder-72 (MRT72), typically characterized by microcephaly, global developmental delay, and speech impairment." (PMID 41465175, 2025). "Biallelic pathogenic variants in METTL5 have been associated with MRT72 (OMIM #618665), a condition characterized by microcephaly, GDD, ID, and behavioral disturbances." (PMID 41465175, 2025). "A further case from Iran described a 13-year-old boy with microcephaly and ID carrying a novel homozygous 10 bp deletion (c.223_224?8del) in the donor splice site of exon 2 of METTL5." (PMID 41465175, 2025). "Despite the microcephaly phenotype common in many Mettl5 KO/KD organisms, neuronal function has never been investigated in Mettl5 KD zebrafish." (PMID 36266443, 2022).
gastric cancer (4 papers, 2021 to 2025). A primary or metastatic malignant neoplasm involving the stomach. "In gastric cancer (GC), high METTL5 expression was associated with poor prognosis." (PMID 41487998, 2025). "In our study, the protein expression of METTL5 was detected in gastric cancer tissues (GCTs) and adjacent tissues by immunohistochemical staining." (PMID 34702266, 2021). "METTL5 protein in gastric cancer tissues (GCTs) was significantly decreased compared with adjacent normal tissues (ANTs) and adjacent intestinal metaplasia tissues (AIMTs) (P < 0.001, respectively)." (PMID 34702266, 2021). "We aimed to investigate the expression and prognostic features of METTL5 in gastric cancer (GC)." (PMID 34702266, 2021).
cardiac hypertrophy (3 papers, 2022 to 2025). "While METTL5 has been implicated in regulating translational efficiency during embryonic differentiation and tumorigenesis, its role in cardiac hypertrophy has only recently been elucidated." (PMID 41487998, 2025). "It has been reported that cardiac hypertrophy can be accelerated by loss of Mettl5 through epitranscriptomic regulation of SUZ12 expression." (PMID 40391221, 2025). "Collectively, these findings identify METTL5 as a novel translational regulator of cardiac hypertrophy via rRNA m6A modification, providing new insights into the molecular basis of cardiac remodeling." (PMID 41487998, 2025). "Functional assays in primary cardiomyocytes, using both gain- and loss-of-function approaches, further confirmed the regulatory role of METTL5 in cardiac hypertrophy." (PMID 41487998, 2025). "As a result, the expression level of METTL5 was reduced in Calcineurin transgenic (CnA-Tg) hearts but remained unaltered in transverse aortic binding (TAC)-induced cardiac hypertrophy." (PMID 35295259, 2022). "To validate the role of SUZ12 in METTL5-mediated inhibition of cardiac hypertrophy, we performed a rescue experiment by knocking down SUZ12." (PMID 35295259, 2022). "Our data indicated that SUZ12 is an important regulator mediating the inhibitory function of METTL5 in cardiac hypertrophy." (PMID 35295259, 2022). "In summary, our study uncovered that METTL5 was a key regulator of cardiac hypertrophy, highlighting the importance of regulation at the step of mRNA translation during the development of heart disease." (PMID 35295259, 2022). "We show that METTL5 promotes stress-induced cardiac hypertrophy mainly via regulating the translation of SUZ12 mRNA." (PMID 35295259, 2022). "The expression levels of fetal genes, including Nppa, Nppb, and Acta1, which are often elevated in cardiac hypertrophy, were further increased in METTL5-cKO TAC hearts." (PMID 35295259, 2022). "In this study, our data indicated that the enhanced cardiac hypertrophy was mainly mediated by the decreased translation of SUZ12 mRNA in METTL5-depleted cardiomyocytes." (PMID 35295259, 2022). "Forced expression of METTL5 in cardiomyocytes repressed cardiac hypertrophy via modulating the translation of SUZ12 mRNA." (PMID 35295259, 2022). "Therefore, we suspected that METTL5 regulated the translational efficiency of SUZ12 mRNA in cardiac hypertrophy." (PMID 35295259, 2022). "In the future, investigation with a model using cardiac-specific overexpression of METTL5 in vivo should be carried out to test the therapeutic potential of controlling mRNA translation via METTL5 in delaying cardiac hypertrophy and the progression of heart failure." (PMID 35295259, 2022). "Next, we asked how METTL5 regulated the SUZ12-mediated signaling in cardiac hypertrophy." (PMID 35295259, 2022). "Taken together, our results suggested that the SUZ12(PRC2)-Mef2d axis could be critical in the regulation of cardiac hypertrophy by METTL5 mainly through modulating the translational efficiency of SUZ12 mRNA." (PMID 35295259, 2022). "It remains unknown whether and how METTL5 regulates cardiac hypertrophy." (PMID 35295259, 2022). "Mechanically, METTL5 can modulate the mRNA translation of SUZ12, a core component of PRC2 complex, and further regulate the transcriptomic shift during cardiac hypertrophy." (PMID 35295259, 2022). "Furthermore, the partial rescue effect in cardiac hypertrophy was also observed in the treatment of SUZ12/PRC2 inhibitors, EED226 and Boc-NH-C4-acid, during METTL5 overexpression." (PMID 35295259, 2022). "Given that PRC2 complex has been recently reported to participate in regulating cardiac hypertrophy, our data could suggest that SUZ12 was a key upstream regulator mediating the METTL5-related cardiac phenotype observed above." (PMID 35295259, 2022).
cardiac hypertrophy (continued). "Multiple key pathways of cardiac hypertrophy, such as Adrenegic signaling and MAPK signaling, were significantly altered in the KEGG analyses, that showed an opposite direction of alteration in si-METTL5 treated NRVMs vs. Ad-METTL5 treated NRVMs." (PMID 35295259, 2022).
intrahepatic cholangiocarcinoma (3 papers, 2024 to 2025). A carcinoma that arises from the intrahepatic bile duct epithelium in any site of the intrahepatic biliary tree. "Loss of Mettl5 inhibits intrahepatic cholangiocarcinoma (ICC) progression." (PMID 41431992, 2025). "Importantly, aberrant upregulation of METTL5‐mediated 18S rRNA m6A modification in intrahepatic cholangiocarcinoma (ICC) correlates with poor survival." (PMID 38797935, 2024).
lung adenocarcinoma (3 papers, 2021 to 2025). A carcinoma that arises from the lung and is characterized by the presence of malignant glandular epithelial cells. "METTL1, METTL3, METTL4, METTL5, METTL6 and METTL13 were associated with poor prognosis in various tumors including liver hepatocellular carcinoma (LIHC), breast invasive carcinoma (BRCA), and lung adenocarcinoma (LUAD)." (PMID 41194259, 2025).
nasopharyngeal carcinoma (3 papers, 2024 to 2025). A carcinoma arising from the nasopharyngeal epithelium. "For example, nasopharyngeal carcinoma (NPC) exhibits elevated levels of METTL5/TRMT112 and its m6A modification at 18S rRNA position 1832 (m6A1832), which enhances neoplastic transformation both in vitro and in vivo." (PMID 40271153, 2025).